INS (insulin)
Diseases named in the same sentence as INS in open-access papers (continued):
Sharing a sentence is not in itself a finding about the gene and the disease.
Insulin resistance (continued). "The metabolic score for insulin resistance (METS-IR) is a new, non-insulin-based fasting index used to measure IR." (PMID 40093882, 2025). "Fasting insulin levels and oral glucose tolerance test (OGTT) were performed to measure insulin resistance and calculate homeostatic model assessment - insulin resistance (HOMA-IR)." (PMID 41586197, 2025). "Rutin has also been reported to reduce insulin resistance by enhancing glucose uptake in insulin-resistant cells in FL83B hepatocytes exposed to high glucose levels and improving insulin signaling via phosphorylated protein kinase C activity suppression." (PMID 40035065, 2025). "To probe whether and which hepatokine participated in the ASPG-associated insulin resistance, we measured several hepatokines’ mRNA levels by quantitative PCR in the WT and LKO livers, and especially paid attention to the hepatokines associated with insulin secretion and insulin resistance." (PMID 40760121, 2025). "The primary metabolic effects of insulin are mediated through the PI3K-Akt pathway; however, it is in this pathway that insulin resistance presents problems." (PMID 40989682, 2025). "At the same time, LXR inhibits the activation of insulin resistance-related c-Jun amino-terminal kinase (JNK) signaling pathway, improves insulin signal transduction, restores insulin sensitivity of cells, and promotes glucose uptake and utilization." (PMID 40650120, 2025). "Consequently, improving VD status may lower insulin resistance and serum insulin levels." (PMID 41573195, 2025). "We conducted a comprehensive systematic review and meta-analysis to evaluate the effects of hesperidin supplementation on insulin resistance and sensitivity, encompassing five outcome measures: HOMA-IR, QUICKI, INS, FBG, and HbA1c." (PMID 41586243, 2025). "In individuals with obesity-related insulin resistance, hypertrophied adipocytes exhibit increased secretion of pro-inflammatory cytokines, such as TNF-α, IL-6, and IL-1β, all of which impair insulin signaling by activating NF-κB and JNK pathways." (PMID 40563357, 2025). "High glucose levels activate NLRP3 inflammasomes, which exacerbate β-cell dysfunction and insulin resistance in both T1DM and T2DM, enhancing inflammation and impairing insulin signaling." (PMID 40507468, 2025). "This suppression decreases the secretion of insulin-sensitizing hormones like adiponectin and increases the expression of monocyte chemoattractant protein-1 (MCP-1), both of which further intensify insulin resistance." (PMID 41301787, 2025). "Insulin Resistance (HOMA-IR): The telehealth group exhibited a significant reduction in HOMA-IR (Δ = −1.4, p < 0.05), reflecting improved insulin sensitivity." (PMID 40978311, 2025). "As leptin resistance and insulin resistance occur simultaneously in T2DM, it is also certainly possible that a synergism of diminished leptin and insulin response leads to reduced CVP neuronal function." (PMID 40078371, 2025). "We assessed insulin resistance based on fasting insulin levels and HOMA-IR, which are surrogate measures for insulin resistance." (PMID 40362793, 2025). "The significant improvements in fasting glucose, fasting insulin, and the HOMA-IR index in the CC group confirm that the supplementation substantially reduces HFD-induced insulin resistance and impaired glucose homeostasis." (PMID 41470796, 2025). "GLUT4 is an insulin-dependent glucose transporter on adipocyte and muscle cells, helps in glucose uptake and GLUT4 is decreased during obesity resulting in insulin resistance." (PMID 40529363, 2025). "We showed that metformin alleviated insulin resistance in mice treated with four doses of COVID‐19 vaccine, as revealed by improved OGTT and ITT indices (p < 0.05) and improved insulin signaling (p < 0.05)." (PMID 41190280, 2025).
Insulin resistance (continued). "Specifically, insulin resistance indices (HOMA and QUICKI), SBP, and insulin concentrations decreased significantly, while HDL and total cholesterol concentrations increased in both groups after the 12-month follow-up period." (PMID 40647247, 2025). "Researchers have found that SIRT3 activation enhances insulin sensitivity through the regulation of insulin signaling, whereas SIRT3 inhibition exacerbates insulin resistance." (PMID 40799515, 2025). "The activation of JAK2 is correlated with the emergence of insulin resistance, and the depletion of JAK2 in adipocytes boosts insulin sensitivity in the liver." (PMID 40271123, 2025). "The IGT&T2D group also exhibited significantly higher levels of variables such as fasting glucose, 2‐h OGTT glucose, 2‐h OGTT insulin and HOMA, along with lower levels of QUICKI, all of which are related to insulin resistance, compared to the NG group." (PMID 40377893, 2025). "Four week’s treatment of TPMD significantly ameliorated insulin resistance in DIO mice, accompanied by marked decrease in fasting plasma insulin levels." (PMID 41473291, 2025). "Sustained ER stress ultimately promotes insulin resistance, exemplified by activation of JNK, which phosphorylates IRS-1 and disrupts insulin signaling." (PMID 41226411, 2025). "In this study, T2DM subjects exhibited elevated fasting glucose and insulin, yielding high HOMA-IR values, highlighting the role of insulin resistance in persistent hyperglycemia despite adequate insulin secretion." (PMID 40509433, 2025). "Hepatic ceramides contribute to hyperglycemia and insulin resistance by inhibiting the action of Akt/PKB, disrupting insulin’s ability to suppress hepatic glucose production and inhibiting glycogen synthesis." (PMID 40564914, 2025). "Cer clearly play a role in diabetic pathophysiology, linking insulin resistance and CVD and mediating the inhibitory effects of saturated fatty acids on insulin signaling." (PMID 40980166, 2025). "TNF‐α reduces insulin‐dependent glucose uptake by impeding serine autophosphorylation of insulin receptor substrate‐1, which inhibits circulating insulin, indicating an involvement of TNF‐α in insulin resistance." (PMID 39355932, 2025). "Hyperandrogenism often leads to insulin resistance (IR) in patients with PCOS3, and testosterone level has been positively correlated with insulin levels in studies." (PMID 40841528, 2025). "It is important to note that higher fasting insulin, higher HOMA-IR,and lower QUICKI mainly reflect hepatic insulin resistance whereasthe assessment of whole-body insulin sensitivity would require additionaldata from a 5-point OGTT or other tests." (PMID 41200836, 2025). "GWIS identified ten SNPs in three loci, including rs4713207 (OR14J1, Pmeta = 3.95 × 10−8) for insulin resistance, rs17708475 (NKAIN2, Pmeta = 4.83 × 10−8) for insulin sensitivity, and rs201613 (MYH3, Pmeta = 1.05 × 10−8) for disposition index." (PMID 40719081, 2025). "Although hepatic insulin resistance (i.e., HOMA‐IR) was unaltered after the intervention (−0.10 ± 1.0 a.u., p = 0.67), peripheral insulin sensitivity (i.e., SIis) increased (0.004 ± 0.006 a.u., p = 0.003)." (PMID 39421964, 2025). "Experiments using adipose tissue cultures from obese horses with insulin resistance and controls revealed that adding SHBG restored levels of INSR, INRS1/2, Akt and Pi3k, implying improved insulin sensitivity, and tended to normalize the fatty acid profile." (PMID 40863113, 2025). "Insulin resistance plays an important role in the pathophysiology of PCOS, as high insulin levels stimulate androgen production by the ovaries, resulting in symptoms such as hirsutism, acne, and anovulation." (PMID 40969606, 2025). "The M + insulin group exhibited significant activation of the IL-17 and JAK-STAT signaling pathways, likely attributable to insulin resistance." (PMID 40565658, 2025).
Insulin resistance (continued). "While HOMA-IR captured direct insulin–glucose dysregulation in 44.4% of obese children, the TG/HDL-C ratio identified dyslipidemic insulin resistance in 38.9% of cases." (PMID 41374006, 2025). "Research has established AIP as an effective surrogate indicator of insulin resistance, with elevated AIP values demonstrating strong inverse correlations with insulin sensitivity." (PMID 41257791, 2025). "Key parameters observed included body weight, glucose tolerance (via glucose tolerance tests), insulin resistance (HOMA-IR), and insulin secretion under glucose stimulation." (PMID 39925816, 2025). "Additionally, the value of the leukocyte mtDNA CN proxy could be better understood by conducting intervention studies that focus on reducing insulin resistance through lifestyle changes or insulin‐sensitizing medications, while also tracking mtDNA CN and cognitive outcomes." (PMID 39579049, 2025). "The assessment process benefits from additional markers of insulin resistance, which include HOMA-IR, fasting insulin, low-density lipoprotein (LDL) cholesterol, triglycerides, and inflammatory cytokines (TNF-α and IL-6)." (PMID 40225541, 2025). "By monitoring insulin levels and calculating HOMA-IR, researchers can assess the combined effects of exercise and functional food interventions on insulin resistance, providing valuable insights into metabolic adaptations." (PMID 39940866, 2025). "In addition, through western blotting analysis of insulin-induced Akt phosphorylation in tissues that strongly influence whole-body insulin sensitivity, particularly liver and skeletal muscle, we found that severe insulin resistance occurred only in liver tissue." (PMID 39948368, 2025). "This was accompanied by decreased glucose sensitivity and increased insulin resistance in Ext1 AKO mice as measured by glucose and insulin tolerance tests, respectively, after 15-weeks of HFD." (PMID 41072794, 2025). "Insulin-resistant individuals, even when matched for BMI, displayed impaired MFO, consistent with mechanistic evidence linking insulin resistance to reduced lipolysis and impaired fatty acid transport." (PMID 41590220, 2025). "Induction of insulin signaling with IGF-1 and reversal of insulin resistance has been shown to suppress α-synuclein aggregation and toxicity in cultured cells." (PMID 40595707, 2025). "In human visWAT, we observed a positive correlation of MTCH2 expression (visMTCH2) with BMI, body fat, fasting plasma insulin (FPI), leptin, homeostatic model assessment for insulin resistance (HOMA-IR), and HDL-cholesterol." (PMID 41044057, 2025). "Acupuncture has been demonstrated to reduce insulin and leptin levels in T2DM patients, increase serum adiponectin levels, alleviate insulin resistance, and regulate glucose and lipid metabolism." (PMID 40568559, 2025). "In a study on 229 obese patients, the metabolic parameters (e.g., plasma insulin, plasma free fatty acid), hepatic insulin resistance, and liver fibrosis of those with MASLD worsened according to the quartiles of adipose tissue insulin resistance." (PMID 39857417, 2025). "They investigated the connection between insulin resistance and the dietary phytochemical index (DPI) and reported that those with greater dietary phytochemical index were far less likely to be insulin resistant and to have hyperinsulinemia." (PMID 40091984, 2025). "β-cell function (HOMA-B) was significantly decreased (P-value = 0.0147), along with increased insulin resistance (HOMA-IR) (P-value = 0.0005) and reduced insulin sensitivity (QUICKI) (P-value = 0.0002) in HDF/STZ mice." (PMID 40814000, 2025). "During insulin resistance in PCOS, higher insulin levels lead to the reduced liver synthesis and reduced secretion of SHBG." (PMID 39959624, 2025).
Insulin resistance (continued). "Homeostasis model assessment of insulin resistance (HOMA-IR), homeostasis model assessment of beta-cell function (HOMA-β), quantitative insulin sensitivity check index (QUICKI) and fasting glucose-to-insulin ratio (G/I ratio) were calculated." (PMID 40094911, 2025). "Insulin resistance, a common feature of PCOS, leads to high circulating insulin levels and increased production of insulin-like growth factor (IGF), both of which are associated with the development and progression of breast cancer." (PMID 40989682, 2025). "Other markers to evaluate IR include the homeostasis model assessment of insulin resistance (HOMA-IR), frequently sampled intravenous glucose tolerance test (FSIGT), oral glucose tests, and the insulin sensitivity index." (PMID 41473239, 2025). "The homeostasis model assessment of insulin resistance (HOMA-IR), which is based on fasting blood glucose (FBG) and insulin levels, is the most widely applied index for assessing IR in clinical practice." (PMID 41010511, 2025). "Homeostatic Model Assessment of Insulin Resistance (HOMA-IR), a mathematical model representing insulin resistance state in individuals, can also evaluate insulin sensitivity." (PMID 40943107, 2025). "With regard to metabolic syndrome, elevated IL-18 levels can contribute to insulin resistance by increasing the production of other inflammatory cytokines like TNF-α and IL-6, which interfere with insulin signaling pathways." (PMID 40277935, 2025). "In a meta-analysis of women with PCOS comparing diets on insulin resistance, the DASH diet was found to significantly improve HOMA-IR, fasting insulin, fasting glucose, BMI, and weight." (PMID 41295220, 2025). "We then calculated insulin resistance/sensitivity, both by HOMA-IR (mostly hepatic insulin resistance) and MATSUDA (mostly total body insulin sensitivity)." (PMID 41276872, 2025). "Insulin resistance, expressed as the HOMA-IR index, was observed in the groups of children with obesity and MASLD, even though the values for glucose and insulin were within the upper range of reference values." (PMID 40429499, 2025). "Homeostatic Model Assessment of Insulin Resistance (HOMA-IR) measures were assessed using the fasting glucose and insulin levels to gauge insulin sensitivity." (PMID 40115254, 2025). "In skeletal muscle cells, glucose is absorbed via glucose transporter 4 (GLUT4), and when insulin signaling is disrupted, such as by AKT, PI3K, and mTORC1, blood glucose levels increase because of insulin resistance." (PMID 41373836, 2025). "In our study, we found that insulin resistance, as measured by HOMA-IR, emerged as a significant predictor of MASLD, indicating the intricate interplay between insulin sensitivity and liver fat accumulation." (PMID 41183221, 2025). "Dysregulation of MPC in type 2 diabetes may exacerbate insulin resistance by limiting pyruvate availability for mitochondrial oxidation and promoting the accumulation of metabolic intermediates, such as diacylglycerols and ceramides, which are known to interfere with insulin signaling pathways." (PMID 40001526, 2025). "Insulin-based indices, such as the homeostatic model assessment for insulin resistance (HOMA-IR), require fasting insulin and glucose measurements." (PMID 40416870, 2025). "Preservation of insulin sensitivity is therefore a priority, especially for individuals with low BCF because they have limited ability to mount a compensatory response to insulin resistance." (PMID 41561051, 2025). "Among calcium signaling molecules, CaMKII has been shown to contribute to adipogenic differentiation, Fas-induced lipolysis, the insulin-induced translocation of GLUT4, and the enhancement of angiotensin II–induced insulin resistance in 3T3-L1 cells." (PMID 40662171, 2025). "Various homeostatic model assessment (HOMA) indices for insulin resistance (HOMA-IR), β-cell function (HOMA-β), and insulin sensitivity (HOMA-S) were calculated." (PMID 40995598, 2025).
Insulin resistance (continued). "The Homeostasis Model Assessment of Insulin Resistance (HOMA-IR) and Insulin Sensitivity Index (ISI) were calculated based on FBG and FINS values." (PMID 39859525, 2025). "Reduces insulin resistance and expression of gluconeogenesis genes (PEPCK and G6Pase), enhances insulin signaling." (PMID 41142236, 2025). "As a result, surrogate measures such as the Homeostasis Model Assessment of Insulin Resistance (HOMA-IR) and the Quantitative Insulin Sensitivity Check Index (QUICKI) are commonly employed." (PMID 40687590, 2025). "Despite the commonly observed high tissue insulin resistance in PCOS, the ovary paradoxically remains sensitive to insulin." (PMID 40362363, 2025). "While GDM is studied in the context of maternal obesity and insulin resistance, the consequences of GDM in lean, insulin sensitive women for offspring health are unclear." (PMID 40021748, 2025). "Various methods are available to assess IR, including the homeostasis model assessment of insulin resistance (HOMA-IR) and the quantitative insulin sensitivity check index (QUICKI), which are commonly used in clinical practice." (PMID 40065340, 2025). "Fasting serum insulin levels rose in HFD (p < 0.01) and HFD + V (p < 0.05) groups, which indicated more severe insulin resistance state." (PMID 40260275, 2025). "Hydroxytyrosol was shown to modulate ER stress markers, which are critical in the development of insulin resistance, by reducing the phosphorylation of PERK, IRE1, ATF6, and JNK, thus enhancing insulin signaling pathways." (PMID 39940428, 2025). "One of the metrics used to assess insulin resistance in clinical studies is the Homeostasis Model Assessment of Insulin Resistance (HOMA-IR), which is calculated based on fasting blood glucose and insulin levels." (PMID 41169463, 2025). "Insulin resistance impairs LEC function through chronic inflammation, oxidative stress, and disrupted insulin signaling pathways, including PI3K/AKT." (PMID 41403736, 2025). "Studies have shown that it is more stable, easily available, and cost-effective than other alternative markers, such as the Homeostatic Model Assessment of Insulin Resistance (HOMA-IR) and the quantitative insulin check index (QUICKI)." (PMID 40948812, 2025). "It was observed that the Homeostatic Model Assessment for Insulin Resistance (HOMA-IR) and fasting serum insulin were significantly elevated in the SCH group compared to the euthyroid group." (PMID 40612820, 2025). "HOMA-IR primarily reflects insulin resistance, calculated as FPG × FINS/22.5, and is influenced by hepatic insulin sensitivity." (PMID 40988275, 2025). "It has been reported that insulin resistance in both Alzheimer’s disease (AD) and T2DM can lead to hyperinsulinemia by saturating insulin-degrading biochemical pathways through impaired insulin signaling." (PMID 41444683, 2025). "ESR1 gene expression inversely correlated with age, obesity markers (eg, BMI, WHR, body fat percentage), and markers of hyperglycemia and insulin resistance (eg, HbA1c, HOMA-IR, insulin) (P < .05)." (PMID 39833659, 2025). "Adipose tissue contributes to insulin resistance by releasing free fatty acids (FFA), and elevated plasma FFA levels enhance hepatic gluconeogenesis, impairing glucose-stimulated insulin responses." (PMID 40060375, 2025). "Low ROS promotes insulin signaling, while high H2O2 activates JNK and inhibits IRS, leading to insulin resistance (IR)." (PMID 41567335, 2025). "As a result, whole-body insulin sensitivity index (WBISI) was lower, and homeostatic model assessment for insulin resistance (HOMA-IR) was greater in participants with IR compared with those with IS (U = 7.00, P < 0.001; U = 6.00, P < 0.001, respectively)." (PMID 40091831, 2025). "In contrast, on a high‐fat diet (HFD), LKO mice exhibited elevated plasma insulin levels and a higher HOMA‐IR, with the maintenance of blood glucose levels indicating the development of insulin resistance." (PMID 41001747, 2025).